ARID4A (AT-rich interaction domain 4A)
Diseases named in the same sentence as ARID4A in open-access papers (continued):
Sharing a sentence is not in itself a finding about the gene and the disease.
laryngeal squamous cell carcinoma (1 paper, 2010). A squamous cell carcinoma that arises from the larynx. "ARID4A expression was also analyzed in 24 pairs of tumor and matched normal tissues from laryngeal squamous cell carcinomas and in 23 pairs of tumor and matched normal tissues from oral tongue squamous cell carcinomas." (PMID 20441585, 2010).
mental disorder (1 paper, 2024). A disease that has its basis in the disruption of mental process. "According to GWAS using data from the UK biobank, a total of 36 missense mutations in the ARID4A gene showed that the allele frequencies were different in the control and mental disorder cases." (PMID 39206162, 2024).
retinoblastoma (1 paper, 2014). A malignant tumor that originates in the nuclear layer of the retina. "ARID1 is perhaps analogous to ARID4A and ARID4B in animals, which associate with the histone deacetylase complex and are involved in male fertility control by acting in the Retinoblastoma (RB) pathway." (PMID 25057814, 2014).
squamous cell carcinoma (1 paper, 2010). A carcinoma arising from squamous epithelial cells. "ARID4A mRNA levels were decreased (≥ 2-fold) in almost half of the squamous cell carcinomas samples (-1.04 to -6.9-fold change, 23 of 47 samples, i.e., 49%) and were increased in some of these samples (1.51 to 6.26-fold change, 7 of 47 samples, i.e., 15%)." (PMID 20441585, 2010).
tumor (9 papers, 1999 to 2025). "Compared with control adenovirus injection, treatment with Arid4a‐expressing adenovirus significantly inhibited tumor growth and lung metastasis." (PMID 40066676, 2025). "Gain‐of‐function and silencing experiments confirmed the inhibitory effect of Arid4a on tumor metastasis in vitro and in vivo." (PMID 40066676, 2025). "Upon Arid4a overexpression, tumor cell proliferation and cell activity were substantially suppressed." (PMID 40066676, 2025). "Results from the TIMER database showed that the expression of ARID1A, ARID2, and ARID4A was positively related to tumor purity (p < 0.05), indicating that these three genes were lowly expressed in the HCC immune microenvironment." (PMID 36034939, 2022). "Knockdown of endogenous ARID4A increased the oncogenicity of carcinoma cells, while ARID4A was found to be drastically down-regulated in tumor tissue." (PMID 28486502, 2017). "Arid4a has also been identified as a potential tumor suppressor of leukemia and prostate cancer." (PMID 40066676, 2025). "Moreover, the migration of MDA‐MB‐231 cells was significantly inhibited by the mutant aa 1–398 but not by the other mutants, indicating that the ARID domain is critical for Arid4a‐induced suppression of tumor metastasis." (PMID 40066676, 2025). "ARID4A is known to be a tumor suppressor in a variety of malignancies." (PMID 28486502, 2017). "In addition, Arid4a knockdown promoted tumor growth and lung metastasis in vivo." (PMID 40066676, 2025). "Thus, expression levels of miR-376c and ARID4A mRNA tended to be opposing in tumor tissue." (PMID 28486502, 2017). "Among the targets of Arid4a, MTSS1, RB1, and PTEN are involved in the suppression of tumor cell metastasis, while TIMP2 is believed to be a suppressor of tumor angiogenesis." (PMID 40066676, 2025). "A large number of genes that function as tumour and growth suppressors, such as PHACTR4 and ARID4A, as well as genes that correspond to chemotherapy/radiotherapy response genes, such as SNAI1 and SNX1, were overexpressed." (PMID 32543350, 2020). "The mRNA expression of ARID3A, ARID3B, ARID4B, JARID1B, JARID1C, JARID2 in tumor tissues was more expressive in normal tissues, ARID1B, ARID3C, ARID4A, ARID5A, ARID5B, JARID1A mRNA expression in tumor tissues were lower than that in the normal tissues (p<0.05)." (PMID 33592583, 2021).
cancer (8 papers, 2012 to 2025). A tumor composed of atypical neoplastic, often pleomorphic cells that invade other tissues. "Arid4a is closely associated with the pathogenic process of human diseases, including male reproductive ability and cancer." (PMID 40066676, 2025). "According to a large scale bioinformatics study encompassing 4,623 tumors from multiple anatomical sites, ARID4A is one of the genes found within the chromatin regulatory element group that exhibits potential driver alterations in one or more cancer types (detailed analysis not shown)." (PMID 28486502, 2017).
infection (2 papers, 2015 to 2025). The state of being infected such as from the introduction of a foreign agent such as serum, vaccine, antigenic substance or organism. "ARID4A is also upregulated post-infection at 12 weeks, but its expression is reduced at the 16-week mark." (PMID 41141600, 2025).
head and neck tumors (1 paper, 2010). "Therefore, similarly to the Hep-2 cell line, most primary head and neck tumors (49%) showed down-regulation of ARID4A transcripts." (PMID 20441585, 2010).
ARID4A also shares sentences with these, for which no sentence is quoted: chronic myelomonocytic leukemia (1 paper); Cirrhosis (1); colorectal cancer (1); hematologic malignancies (1); hepatocellular adenoma (1); hepatocellular carcinoma (1); Infertility (1); male infertility (1); myelofibrosis (1); myeloid malignancies (1); osteosarcoma (1).